TLR4 (toll like receptor 4)
Diseases named in the same sentence as TLR4 in open-access papers (continued):
Sharing a sentence is not in itself a finding about the gene and the disease.
liver fibrosis (259 papers, 2009 to 2026). "Polymorphisms in the Toll-like receptor 4 (TLR4) and IL-17 cytokine genes play a role in liver fibrosis progression among patients with MASLD." (PMID 40332363, 2025). "Polymorphisms in the Toll-like receptor 4 (TLR4) and IL-17 cytokine genes are involved in the progression of liver fibrosis in patients with MASLD." (PMID 40332363, 2025). "While TLR4 signaling is implicated in the development of alcohol-related liver disease and other forms of liver fibrosis, the specific role of hepatocyte-expressed TLR4 needs to be further investigated in these diseases." (PMID 40595432, 2025). "A lower degree of liver fibrosis was documented in studies of carbon tetrachloride- or bile duct ligation-induced liver fibrosis in TLR4-mutant mice along with mutations in MyD88, CD14, TRIF and LBP." (PMID 39201329, 2024). "It has been shown in another study that plumbagin has anti-fibrotic action by inhibiting the NF-kβ/TLR-4 pathway, which is linked to inflammatory responses, and therefore reducing liver fibrosis." (PMID 36985782, 2023). "Activation of the TLR4-myD88-NFκB signaling pathway, an important pathway associated with hepatic fibrosis and HCC, can lead to the release of downstream inflammatory factors and induce the production of IL-1, IL-6, and TNF-α." (PMID 38074679, 2023). "On the contrary, mice with deficiencies of components of the TLR4 signaling pathway are less susceptible to liver fibrosis." (PMID 34422075, 2021). "Rationale: Liver fibrosis is frequently associated with gut barrier dysfunction, and the lipopolysaccharides (LPS) -TLR4 pathway is common to the development of both." (PMID 33391458, 2021). "Previous research has shown that B. fragilis lipopolysaccharide can activate Toll-like receptor 4, which in turn has been associated with liver fibrosis and was suggested as a potential mechanism in stricturing CD." (PMID 34168621, 2021). "Toll-like receptor 4 (TLR-4) activation is implicated to play a key role in both inflammatory and fibrogenic pathways, acting on KCs and participating in the process of liver fibrosis." (PMID 33933107, 2021). "In accordance with these studies, we reported that liver fibrosis induced by DEN+CCl4 injection was associated with significantly increased expression of TLR4 in the liver tissue." (PMID 34045968, 2021). "TLR4 is the main target for lipopolysaccharide (LPS) and is largely involved in the inflammatory reaction associated with liver fibrosis." (PMID 34045968, 2021). "PTPRO causes ulcerative colitis through TLR4/NF-KB signaling pathway and plays a role in liver fibrosis by affecting PDGF signaling in HSC activation." (PMID 33462260, 2021). "Taken together, our data suggested that TLR4 deficiency aggravated hepatic fibrosis in C57BL/10 mice infected by C. sinensis." (PMID 33469517, 2020). "Overall, it has been found that loss of hepatic stellate cell TLR4-MyD88 signaling reduces development of hepatic fibrosis." (PMID 33542720, 2020). "All these results indicate that the NF-κB and JNK pathways, associated with downstream of TLR4 signaling, are involved in miR-14a-5p-mediated regulation of hepatic fibrosis." (PMID 29348414, 2018). "TLR4 D299G and T399I SNPs were reported to be associated with protection from hepatic fibrosis by reducing TLR4-mediated fibrogenic signaling." (PMID 30034633, 2018). "In chimeric C3H/HeJ mice with TLR4 mutation in HSCs, remission of hepatic fibrosis induced by exposure to LPS indicated a main role for HSCs in hepatic inflammation and fibrosis." (PMID 29321784, 2017). "Hepatic fibrosis and cirrhosis have been linked to TLR4, with TLR4-deficient mice displaying less fibrosis in chemically (carbon tetrachloride, CCl4 or thioacetamide, TAA) or bile duct ligation (BDL)-induced fibrosis models." (PMID 27391331, 2016). "As a modulator of innate immunity and LPS response, TLR4 has been widely implicated in various liver disorders including liver fibrosis and hepatocellular carcinoma." (PMID 27391331, 2016).
liver fibrosis (continued). "Upon activation of TLR4, macrophages in the liver release inflammatory agents that cause liver fibrosis." (PMID 24400890, 2014). "A recent study reported that TLR4 gene polymorphisms are good prognostic predictors and are associated with protection from liver fibrosis among Caucasians." (PMID 25177689, 2014). "Genetic variations in TLR4 gene have been linked to susceptibility to several infectious agents such as bacterial infection, viral infection, malaria, hepatic fibrosis, and HCV-associated HCC." (PMID 25177689, 2014). "TLR4 SNPs also modulate the risk of liver fibrosis in Caucasians with chronic hepatitis C infection." (PMID 24349054, 2013). "A recent work has implicated TLR4, as expressed on hepatic stellate cells (HSCs), as a key driver of liver fibrosis, owing to the stimulatory effect of TLR4 activation on the transforming growth factor β1 (TGFβ1) pathway." (PMID 23441159, 2013). "Specific single nucleotide polymorphisms (TLR D299G and T399I) are associated with less hepatic fibrosis by decreased TLR4-mediated signaling." (PMID 23087650, 2012). "A recent report documents the discovery of a single nucleotide polymorphism (T399I) in TLR4 that can significantly reduce the risk of hepatic fibrosis." (PMID 22927965, 2012). "Bone-marrow chimeric mice with a TLR4 deficiency in recipient liver cells, including HSCs, were resistant to liver fibrosis." (PMID 22973518, 2012). "It has been reported evidence of an association of hepatic fibrosis and angiogenesis by TLR-4 through MyD88 on liver endothelial cells." (PMID 22114589, 2011). "The activation of both HSCs and Kupffer cells that express TLR4 is associated with the progression of liver fibrosis." (PMID 20706677, 2010). "In contrast to the reduced risk of early acute allograft rejection, TLR4 SNPs are associated with delayed progression of hepatic fibrosis." (PMID 20964825, 2010). "The conclusion is that TLR4 D299G and T399I SNPs that are associated with protection from hepatic fibrosis reduce TLR4-mediated inflammatory and fibrogenic signaling and lower the apoptotic threshold of activated HSCs." (PMID 20862346, 2010). "The current study aimed to investigate whether the IL17 (A7448G and G197A) and TLR4 (Asp299Gly and Thr399Ile) gene polymorphisms are associated with increased liver fibrosis stages in MASLD patients." (PMID 40332363, 2025). "Notably, OATD-01 suppressed the MASH-mediated elevation in Lpl expression, which is associated with liver fibrosis via the propagation of cholesterol accumulation and inflammatory TLR4 signaling." (PMID 40510344, 2025). "The TLR4-MyD88 pathway is closely associated with developing liver fibrosis." (PMID 39335657, 2024). "Deficiency or mutation of TLR4 in the alcoholic liver disease and in the liver fibrosis models alleviates the symptoms of the disease due to reduced production of proinflammatory mediators and no free radical production, which results in fewer fatally damaged hepatocytes." (PMID 39769138, 2024). "The same consequence of TLR4 was confirmed in liver fibrosis caused by C. sinensis." (PMID 36693049, 2023). "By applying TLR4 antibodies or TLR4 deficient mice, liver fibrosis is alleviated." (PMID 35990625, 2022). "Notably, in a mouse model of liver fibrosis it was shown that reduction of FC accumulation in activated HSCs downregulated TLR4 signaling; this resulted in an increase of Bambi expression, which was associated with a reduction of liver fibrosis." (PMID 30483502, 2018). "Therefore, CA-induced protection against liver fibrosis is associated with the HMGB1/TLR4/NF-κB pathway." (PMID 29403377, 2017). "In addition, liver endothelial cells (LECs) can express TLR4 signaling to regulate angiogenesis through MyD88 pathway, linked to the development of liver fibrosis." (PMID 25153081, 2014).
liver fibrosis (continued). "Also, it was shown that TLR4 SNPs, rs4986790 (D299G) and rs4986791 (T399I), are associated with protection from liver fibrosis, possibly through conformational changes of the protein, thereby affecting its interaction with other proteins." (PMID 25177689, 2014). "TLR4 is the primary LPS receptor, and TLR4 polymorphisms are closely related to liver fibrosis." (PMID 22927965, 2012). "Whether the synergistic regulation of TLR2 and TLR4 is also applicable to the pathogenic process of O. viverrini deserves further investigation in future studies, which may provide more possibilities to unravel liver fibrosis in liver flukes." (PMID 36693049, 2023). "We observed decreased FXR expression, increased TLR4 expression and alterations in ferroptosis features in both the rat liver fibrosis and the LX-2 cell collagen deposition model." (PMID 40278581, 2025). "Rifaximin also significantly lowered TLR4 expression, consistent with findings that it inhibits the LPS/TLR4 pathway in liver fibrosis models." (PMID 40526631, 2025). "Otherwise, Astragalus polysaccharide alleviated alcoholic-induced hepatic fibrosis by inhibiting TLR4/JNK/NF-κB/MyD88 pathway." (PMID 40771890, 2025). "Phenolic acids can also inhibit the development of liver fibrosis by acting on the HMGB1/TLR4/NF-κB pathway." (PMID 41154556, 2025). "The plasma levels of the IL17A cytokine (Kruskal–Wallis test, p = 0.02427), IL17F cytokine (Kruskal–Wallis test, p = 0.02575), and TLR4 (Kruskal–Wallis test, p < 0.0001) were significantly different among patients with various stages of liver fibrosis." (PMID 40332363, 2025). "The plasma level of TLR4 differed across liver fibrosis stages, with patients in advanced fibrosis stages showing lower levels of TLR4 compared to those with moderate fibrosis." (PMID 40332363, 2025). "The TLR4/NF-κB pathway (β = 0.570) directly promoted liver fibrosis, whereas the Nrf2/Keap1 pathway (β = −0.486) inhibited it (P < 0.01)." (PMID 40826133, 2025). "We concluded that alpha-pinene reduced CCl4-induced liver fibrosis by lowering oxidative stress, suppressing liver inflammation, and inhibiting TLR4/NF-κB, TGF-β/Smad3, and PI3K/Akt/mTOR signaling pathways." (PMID 39968080, 2025). "PQ and Tau primarily affected liver fibrosis through three key nodes: the Nrf2/Keap1 pathway, the TLR4/NF-κB pathway, and tight junction proteins and mucin genes." (PMID 40826133, 2025). "PLS-PM results indicated that Tau positively affected the Nrf2/Keap1 pathway and negatively modulated the TLR4/NF-κB pathway, thereby improving intestinal barrier function and alleviating liver fibrosis." (PMID 40826133, 2025). "Lipopolysaccharides (LPSs) derived from the intestine have been reported as a major factor in the progression of liver fibrosis through Toll-like receptor 4 (TLR4) signaling." (PMID 38673992, 2024). "FSE can inhibit the expression of inflammatory factors and fibrotic cytokines, reduce liver injury, and inhibit the development of liver fibrosis through TLR4/MyD88/NF-κB and TGF-β/smads signaling pathways." (PMID 39359922, 2024). "For example, a polysaccharide from the roots of Codonopsis pilosula can promote the activation of HSCs in vivo and in vitro through the combined action of TGF-β1/Smad3 and TLR4/NF-κB signaling pathways, eventually promote liver fibrosis." (PMID 39359922, 2024). "Animal studies in liver fibrosis provide evidence for a role of TLR4 in the pathogenesis of liver fibrosis." (PMID 39201329, 2024). "This study investigated the possible associations between the plasma levels of inflammatory markers, IL17A/F, and TLR4 and their connections with the degree of steatosis and hepatic fibrosis among patients with MASLD." (PMID 39335657, 2024). "Blocking TLR4 signaling in mice or reducing hepatic exposure to intestinal microorganisms improves liver fibrosis." (PMID 39063116, 2024).
liver fibrosis (continued). "LPS is a potent inducer of the activation of hepatic stellate cells (HSCs) via binding to TLR4, and this can strongly drive liver fibrosis progression and, consequently, liver cirrhosis, fostering a background for HCC progression." (PMID 38673992, 2024). "The combination of the bacterial metabolites LPS and TLR4 plays a critical role in the development of hepatic fibrosis by activating intrahepatic fibrogenic cells." (PMID 39063116, 2024). "This study demonstrated that AHCC inhibited HSCs activation by inducing cytoglobin through the TLR2-SAPK/JNK pathway and suppressing collagen production via the TLR4-NF-κβ pathway, resulting in the prevention of liver fibrosis progression." (PMID 39316687, 2024). "LPS is a specific ligand for TLR4 on HSCs membranes, it can trigger more than one of signaling pathways to activate HSCs to promote liver fibrosis, including NF-κB and MAPK." (PMID 39359922, 2024). "For this purpose, our goal was to investigate the potential therapeutic value of EPO against TAA-induced hepatic fibrosis by concentrating on TLR4 and PI3K/Akt signaling pathway modification." (PMID 37649466, 2023). "Further data showed that AAV9-mediated PTRF knockdown inhibited TLR4 signaling and alleviated hepatic fibrosis in NAFLD + CIA rats." (PMID 37346294, 2023). "The in-vitro research indicates that andrographolides administration can prevent liver fibrosis by blocking the TGF-1/Smad2 as well as TLR4/NF-kβ p50 pathways and attenuating the expression of profibrotic and proinflammatory proteins." (PMID 36985782, 2023). "LPS is able to augment TNF-α production and activate the toll-like receptor 4 (TLR-4) pathway, thereby inducing a hepatic inflammatory response, leading to the progression of liver fibrosis and HCC." (PMID 37361533, 2023). "For instance, in a case of liver sterile inflammation, Dectin‐1 dampens rather than potentiates the inflammatory response induced by TLR4, which resulted in reduced liver fibrosis." (PMID 36114607, 2023). "For instance, CircPWWP2A has been suggested to enhance hepatic stellate cells (HSCs) growth and activation and liver fibrosis by acting as the sponge of miR-203 and miR-223, which then up-regulate Fstl1 and Tlr4, respectively." (PMID 37371520, 2023). "A question to ponder is that TLR2 and TLR4 appear to be a synergistic promoter of C. sinensis-induced liver fibrosis." (PMID 36693049, 2023). "Further mechanistic studies demonstrate that CircPWWP2A promotes HSC growth and activation as a sponge of miR-203 and miR-223, which then promotes Fstl1 and TLR4 levels, respectively, and eventually promotes liver fibrosis." (PMID 37371520, 2023). "When LPS reaches the liver, tumor growth factor-β signal is activated through suppression of bone morphogenetic protein and activin membrane-bound inhibitor expression in hepatic stellate cells via toll-like receptor 4, and liver fibrosis is promoted." (PMID 37686272, 2023). "TLR4 stimulation promotes liver fibrosis by downregulating Bambi, an endogenous decoy receptor for TGF-β, and upregulating the TGF-β/Smad signaling pathway." (PMID 38202710, 2023). "AAV9-mediated PTRF knockdown inhibited TLR4 signaling and alleviated hepatic fibrosis in NAFLD + CIA rats." (PMID 37346294, 2023). "It is suggested that ICQA protects against liver fibrosis induced by CCl4 by inhibiting the HMGB1/TLR4/NF-κB signaling pathway." (PMID 38202710, 2023). "The interaction between LPS and hepatocyte Toll-like receptor-4 (TLR4) has been shown to be crucial in hepatocarcinogenesis through inflammation, chronic liver injury, and liver fibrosis." (PMID 36612207, 2022). "Another study also revealed that TLR4 mediates inflammation and hepatic fibrosis induced by chronic intermittent hypoxia in rats." (PMID 35280860, 2022). "Previous studies have shown that TLR4 in fibrotic liver tissue is increased, and positively correlated with the degree of liver fibrosis." (PMID 36579341, 2022).
liver fibrosis (continued). "LPS, which promotes the transformation of HSCs into fibroblasts through the TLR4-NF-κB signalling pathway, induces liver fibrosis." (PMID 35572649, 2022). "Mechanistically, JMJD2D contributes to HSC activation and hepatic fibrosis progression by facilitating the transcription of toll-like receptor 4 (TLR4) through H3K9me2/3 demethylation, subsequently activating TLR4/NF-κB signaling in HSC." (PMID 35740507, 2022). "TLR4 enhances the chemotaxis of Kupffer cells and activation of hepatic stellate cells (HSCs), promoting liver fibrosis." (PMID 36013073, 2022). "And in patients with liver fibrosis caused by HCV, inhibition of TLR4 is also related to the alleviation of fibrosis." (PMID 35990625, 2022). "The results suggested that CIH induced liver fibrosis by TLR4/MyD88/MAPK/NF-kB signaling pathways in DIO mice." (PMID 36187780, 2022). "We have reported the positive association of the cyclooxygenase 2 (COX-2)/prostaglandin E2 (PGE2) axis with liver fibrosis induced by Schistosoma japonicum (Sj) infection, and TLR4 signaling controlled this axis." (PMID 35461268, 2022). "Our results showed that the MyD88 signaling pathway was activated in HSCs and promoted CCl4-induced liver fibrosis, which is consistent with previous studies that LPS/TLR4/MyD88 signaling is involved in the activation of HSCs during liver injury." (PMID 35484116, 2022). "This complex then enters the liver through the circulation of the portal vein, triggering a cascade of intracellular signals in liver through TLR4, which eventually leads to exacerbated liver fibrosis, cirrhosis and even liver cancer." (PMID 36579341, 2022). "the main mechanism by which liver fibrosis occurs, in this case, is the combination of the bacterial metabolites LPS and TLR4, further activating key cells in the liver fibrosis process." (PMID 35222022, 2022). "TLR4 protein expression in rats with liver fibrosis was further increased compared to those exposed to chronic psychological stress (p < 0.001)." (PMID 36579341, 2022). "DAMPs can upregulate as well as amplify fibrotic responses in diseases such as renal and hepatic fibrosis, lesional skin and lung in scleroderma patients, as well as in Tlr4 mutant mice, and augment TGFβ-1 signaling." (PMID 35912101, 2022). "In conclusion, the current study suggests that S100A8 stimulates NLRP3 inflammasome-dependent pyroptosis in macrophages via activating TLR4/NF-κB signaling and inducing ROS abundance, which finally facilitates the progression of liver fibrosis." (PMID 36429008, 2022). "For rats with liver fibrosis exposed to chronic psychological stress, the TLR4 expression level was more significantly increased, and significantly different (p = 0.008), compared with rats with liver fibrosis and those with chronic psychological stress." (PMID 36579341, 2022). "The taurine pathway plays an antioxidant role in acute liver failure, and it can inhibit liver injury and liver fibrosis by inhibiting TLR4/NFKB and and TxNiP/NLRP3 pathways." (PMID 36278176, 2022). "When broad-spectrum antibiotics were utilized to reduce bacterial translocation and TLR4 dependent macrophage activation, liver fibrosis in mice was significantly reduced." (PMID 35990625, 2022). "The gut microbiome is the primary source of the portal LPS, which can be recognized by the presence of toll-like receptor 4 in intestinal epithelial cells, promoting intestinal barrier injuries and liver fibrosis development." (PMID 36159870, 2022). "Breviscapin reduces inflammatory factors by killing TLR4/NF-κB signaling pathway, which can reduce liver fibrosis by decreasing apoptotic response, blocking oxidative stress, and inhibiting inflammation." (PMID 35529927, 2022). "In conclusion, S100A8-mediated NLRP3 inflammasome-dependent pyroptosis by TLR4/NF-κB activation and ROS production in macrophages facilitates liver fibrosis progression." (PMID 36429008, 2022).